HPGDS (hematopoietic prostaglandin D synthase)
Description:
Bifunctional enzyme which catalyzes both the conversion of PGH2 to PGD2, a prostaglandin involved in smooth muscle contraction/relaxation and a potent inhibitor of platelet aggregation, and the conjugation of glutathione with a wide range of aryl halides and organic isothiocyanates. Also exhibits low glutathione-peroxidase activity towards cumene hydroperoxide.
Synonyms: H-PGDS; GSTS; PGDS; PGD2; GSTS1-1; GSTS1
Tractability: Small molecule: a structure with a bound ligand is known; a high-quality ligand is known; it has a high-quality binding pocket; it belongs to a druggable protein family. PROTAC: its protein half-life has been measured; a small molecule that binds it is known.
Target class: Enzyme; Transferase
Gene: Protein-coding gene on chromosome 4 (94,298,507 to 94,342,876, reverse strand). Ensembl gene ENSG00000163106.
Subcellular location: Cytoplasm
Subcellular location (Human Protein Atlas): Cytosol; Vesicles; Nucleoplasm
Pathways (Reactome):
Metabolism: Glutathione conjugation; Synthesis of Prostaglandins (PG) and Thromboxanes (TX)
Gene Ontology:
Molecular function: calcium ion binding; glutathione transferase activity; magnesium ion binding; prostaglandin-D synthase activity; protein binding; protein homodimerization activity
Biological process: prostaglandin metabolic process; glutathione metabolic process; locomotory behavior; signal transduction; cyclooxygenase pathway
Cellular component: cytosol; cytoplasm
Genetic constraint (gnomAD): Loss-of-function variants: 18 observed, 11.87 expected, observed/expected ratio (o/e) 1.52, 90% interval 1.03 to 1.92. The upper end of that interval is the gene's LOEUF score, 1.92, which puts it in group 6 of 6, group 1 being the genes least tolerant of losing a copy. Missense variants: 118 observed, 121.1 expected, observed/expected ratio (o/e) 0.97, 90% interval 0.84 to 1.13. Synonymous variants: 43 observed, 40.53 expected, observed/expected ratio (o/e) 1.06, 90% interval 0.83 to 1.37.
Homologues: Orthologues: chimpanzee HPGDS (99% identical), macaque HPGDS (98% identical), pig HPGDS (89% identical), dog HPGDS (87% identical), guinea pig HPGDS (85% identical), rabbit HPGDS (83% identical), rat Hpgds (81% identical), mouse Hpgds (80% identical), tropical clawed frog hpgds (45% identical), Drosophila melanogaster GstS1 (36% identical), Caenorhabditis elegans gst-20 (34% identical). Paralogues in human: GSTM4 (27% identical), GSTM1 (26% identical), GSTM3 (26% identical), GSTM2 (25% identical), GSTA3 (24% identical), GSTM5 (24% identical), GSTA1 (24% identical), GSTA2 (24% identical), GSTP1 (24% identical), GSTA4 (23% identical), GSTA5 (23% identical).
Diseases named in the same sentence as HPGDS in open-access papers:
HPGDS is named in the same sentence as 304 diseases in open-access papers, as found by Europe PMC text mining. Sharing a sentence is not in itself a finding about the gene and the disease. The quoted sentences say what the papers report.
breast carcinoma (29 papers, 1990 to 2025). "The results showed that JAK2, HPGDS, AR and PARP1 had good potential for targeted treatment of breast cancer." (PMID 38872110, 2024).
malaria (26 papers, 2013 to 2025). Malaria is a serious and sometimes fatal disease caused by a parasite that commonly infects a certain type of mosquito which feeds on humans. "HPGDS (Hematopoietic prostaglandin D synthase) is an integral membrane glycoprotein, which is related to various diseases including blood system diseases and malaria." (PMID 36275756, 2022).
asthma (24 papers, 2008 to 2025). "Tc2 cells express hPGDS, and hPGDS-positive Tc2 cells are increased in eosinophilic asthma and correlated with blood eosinophil counts in asthma patients." (PMID 34011519, 2021). "The frequency of hPGDS-positive Tc2 cells was correlated with blood eosinophil counts in the asthma cohort." (PMID 34011519, 2021). "Several patents and patent applications for hPGDS inhibitors as therapeutic option in allergic inflammation, asthma, chronic obstructive pulmonary disease and other inflammatory diseases have been issued." (PMID 31226822, 2019). "Their data suggests that contrary to the role of H-PGDS in driving Th2-like responses in models of asthma, HPGDS may act as an internal braking signal essential for bringing about the resolution of Th1-driven delayed type hypersensitivity reactions." (PMID 22791937, 2012). "In 2015, Phase I clinical trial (NCT 02397005) was initiated to evaluate tolerability and pharmacokinetics of the selective and reversible hPGDS inhibitor ZL-2102 for treatment of COPD, asthma and idiopathic pulmonary fibrosis." (PMID 31226822, 2019).
lung carcinoma (23 papers, 1992 to 2024). "Analyses of the protein levels showed that levels of HPGDS were significantly lower in 7 out of 10 common tumors: BRCA, colon cancer, ovarian cancer (OV), uterine corpus endometrial carcinoma (UCEC), lung cancer, head and neck cancer, and liver cancer." (PMID 36291099, 2022). "Meta-analysis of 6 hub genes of lung cancer was performed by ONCOMINE databases, and showed that UGT1A6 and DGAT1 were upregulated, while HPGDS and LPL were downregulated." (PMID 33050938, 2020). "HPGDS plays an important role in the occurrence and development of lung cancer, however, its catalytic product, PGD2, has been confirmed to be a mast cell-derived anti-angiogenic factor for lung cancer." (PMID 36324576, 2022).
bladder cancer (14 papers, 2010 to 2025). "Few studies had reported that the six genes (TBXAS1, GYPC, HPGDS, GAB3, ADORA3, and FOLR2) had strong correlation with bladder cancer." (PMID 36275756, 2022).
colitis (13 papers, 2016 to 2024). Inflammation of the colon. "In order to determine whether the pro-resolving effects of endogenous 15d-PGJ2 on DSS-induced colitis attributable to HPGDS, we utilized HQL-79, a commonly used inhibitor of this enzyme." (PMID 33633749, 2021). "In contrast 15-PGDH, GPx-1/2 and hPGDS were increased in Se-Sup group compared to Se-Def and Se-Ade groups suggesting that Se at different dietary concentrations differentially regulates the inflammation in experimental colitis." (PMID 30063735, 2018). "Additionally, hematopoietic PGD synthase (hPGDS) protein was detected in the colons of both WT and mPGES-1−/− mice, with no change in expression levels following colitis induction." (PMID 39596393, 2024).
Obesity (13 papers, 2008 to 2025). Accumulation of substantial excess body fat. "As obesity is associated with increased inflammation in various tissues, including the ovary, the expression and localization of CD45 and HPGDS were further evaluated in HFD ovaries." (PMID 40141675, 2025). "Gene expression of key enzymes involved in eicosanoid production was reduced (COX1, HPGDS, LPGDS, ALOX15, all p ≤ 0.05) or unaltered (COX2, ALOX5) during critical illness, irrespective of obesity." (PMID 28303483, 2017).
COVID-19 (12 papers, 2020 to 2025). A disease caused by infection with severe acute respiratory syndrome coronavirus 2. "ILC2 cells from COVID-19 patients downregulated the expression of HPGDS (adj.p = 9.9e-11), which encodes an enzyme that plays a role in the prostanoid metabolic pathway." (PMID 39026668, 2024).
allergic disease (9 papers, 2012 to 2023). An immune response that occurs following re-exposure to an innocuous antigen, and that requires the presence of existing antibodies against that antigen. "The genes HPGDS and CYP11A1 were part of both lipid metabolism and allergy subsets, in line with their function in prostaglandin metabolism." (PMID 36725846, 2023). "However, whether different hPGDS variants are associated with allergic disease or other inflammatory disorders has not been clarified to date." (PMID 31226822, 2019). "The study shows that the HPGDS inhibitor improved AD symptoms, possibly due to a reduction in PGD2 production, indicating that HPGDS might be a potential therapeutic target for allergic diseases." (PMID 36003397, 2022).
Alzheimer disease (8 papers, 2012 to 2022). A progressive, neurodegenerative disease characterized by loss of function and death of nerve cells in several areas of the brain leading to loss of cognitive function such as memory and language. "Expression of DP1 and HPGDS is also increased in the brains of patients with Alzheimer's disease." (PMID 22778499, 2012).
colorectal cancer (8 papers, 2012 to 2022). A primary or metastatic malignant neoplasm that affects the colon or rectum. "Consistent with previous results, we detected low expression of HPGDS in colorectal cancers in this study." (PMID 36291099, 2022).
type 2 diabetes mellitus (6 papers, 2013 to 2025). A type of diabetes mellitus that is characterized by insulin resistance or desensitization and increased blood glucose levels. "Through Mendelian randomization we demonstrate potentially causal effects of FGF21 and HAVCR1 on risk for type 2 diabetes, of HPGDS on BMI, and of OXT on risk for lacunar stroke." (PMID 40225784, 2025).
allergic rhinitis (5 papers, 2017 to 2025). Inflammation of the nasal mucous membranes caused by an IgE-mediated response to external allergens. "Previously, literature reported that HPGDS inhibitor TAS-205 has been investigated in Guinea pig models of allergic rhinitis." (PMID 40275384, 2025). "Further, hPGDS expression in macrophages was reported in the nasal mucosa of allergic rhinitis patients, pulmonary macrophages in acute respiratory distress syndrome and human adipose tissue macrophages." (PMID 31226822, 2019). "HPGDS in healthy nasal mucosa is expressed only in mast cells, but in allergic rhinitis and nasal polyps also in infiltrating inflammatory cells including eosinophils." (PMID 28770200, 2017). "In a recent preclinical study of allergic rhinitis, the hPGDS inhibitor TAS-205 in combination with montelukast showed a significant additive inhibitory effect on eosinophil infiltration and nasal obstruction in the late phase, when compared to treatment with either active agent alone." (PMID 33919453, 2021). "Similarly, infiltrating eosinophils in the nasal mucosa of patients with allergic rhinitis express hPGDS." (PMID 31226822, 2019). "Similarly, higher hPGDS expression was observed in tissue from allergic rhinitis patients." (PMID 33919453, 2021). "In allergic rhinitis, hPGDS but not LPGDS expression could be detected in the nasal mucosa, while various hPGDS expressing infiltrating cells were identified." (PMID 31226822, 2019). "Higher levels of hPGDS but not LPGDS expression could also be found in the nasal mucosa of patients with allergic rhinitis, where mast cells could be identified as hPGDS+ cells next to infiltrating eosinophils, macrophages and lymphocytes." (PMID 31226822, 2019). "In summary, therapeutically blocking hPGDS and PGD2 biosynthesis could be beneficial to delay the onset of allergic asthma, reduce eosinophilic and Th2 type inflammation, alleviate symptoms including allergic rhinitis and cough as well as reduce airway remodelling." (PMID 31226822, 2019).
Duchenne muscular dystrophy (5 papers, 2019 to 2025). Duchenne muscular dystrophy (DMD) is a neuromuscular disease characterized by rapidly progressive muscle weakness and wasting due to degeneration of skeletal, smooth and cardiac muscle. "• Novel therapeutic approach: PK007 is a selective hematopoietic prostaglandin D2 synthase (HPGDS) inhibitor targeting Duchenne Muscular Dystrophy (DMD)." (PMID 40275384, 2025). "Another preclinical HPGDS inhibitor was explored in a Duchenne Muscular Dystrophy murine model." (PMID 39177131, 2024). "Beyond allergic inflammation as the expected indication ofor hPGDS inhibitors, another Phase I clinical trial investigating safety and pharmacokinetics of hPGDS inhibitor TAS-205 in 23 boys with Duchenne’s muscular dystrophy could be completed successfully in 2018." (PMID 31226822, 2019). "This HPGDS inhibitor, TAS-205, was developed by Taiho Pharmaceutical Co., Ltd, aimed for the treatment of Duchenne Muscular Dystrophy." (PMID 39177131, 2024).
lung diseases (5 papers, 2011 to 2022). "Regarding limitations, questions about the therapeutic potential remain and further investigation will be required to establish the benefits of hPGDS inhibition in pulmonary disease." (PMID 34769126, 2021).
acute myeloid leukemia (4 papers, 2017 to 2024). Acute myeloid leukemia (AML) is a group of neoplasms arising from precursor cells committed to the myeloid cell-line differentiation. "Our enrichment analysis results support previous findings, showing that DLK1 and HPGDS were involved in acute myeloid leukemia." (PMID 38184718, 2024).
adenoma (4 papers, 2014 to 2023). A neoplasm arising from the epithelium. "In an opposite effect, knockout of the gene for hematopoietic prostaglandin D synthase (HPGDS) caused more adenomas in ApcMin/+ mice." (PMID 24729479, 2014). "Our earlier work showed that knockout of hematopoietic prostaglandin D synthase (HPGDS, an enzyme that produces prostaglandin D2) caused more adenomas in ApcMin/+ mice." (PMID 24729479, 2014).
atopic dermatitis (4 papers, 2015 to 2022). "In atopic dermatitis, Langerhans cells, plasmatoid and myeloid dendritic cells express hPGDS and are able to modulate PGD2 production upon activation with exogenous stimuli like bacterial LPS." (PMID 31226822, 2019). "Another study found that peripheral blood DCs as well as tissue plasmacytoid and myeloid DCs in atopic dermatitis patients stained positive for hPGDS." (PMID 31226822, 2019).
eosinophilia (4 papers, 2012 to 2024). "Hence, our findings boost the status of hPGDS-derived PGD2 to an important host-derived mediator of S. mansoni infection-elicited systemic eosinophilia." (PMID 39173086, 2024).
glioma (4 papers, 2019 to 2024). A benign or malignant brain and spinal cord tumor that arises from glial cells (astrocytes, oligodendrocytes, ependymal cells). "A comparison of the expression level of HPGDS with the mutation status of IDH1 showed that HPGDS was more highly expressed in IDH1 wild-type gliomas, especially grade 2 and 4 gliomas." (PMID 36291099, 2022). "The expression level of HPGDS was significantly positively correlated with the grade of glioma, and high levels of HPGDS predicted a poor prognosis." (PMID 36291099, 2022). "Analysis of the CGGA database showed that the expression level of HPGDS in high-grade gliomas was significantly higher than that in low-grade gliomas, suggesting that the HPGDS expression levels were positively correlated with tumor grade." (PMID 36291099, 2022). "H-PGDS/HPGDS expression is also upregulated in lower grade glioma." (PMID 36765904, 2023). "Changes in H-PGDS/HPGDS expression can be specific to gliomas." (PMID 36765904, 2023). "We therefore hypothesized that HPGDS may be involved in mediating the malignant progression of gliomas." (PMID 36291099, 2022). "Although the survival time of patients with high HPGDS expression was also shorter in grade 4 glioma, the difference was not statistically significant, which may be related to the poor overall prognosis of grade 4 glioma patients." (PMID 36291099, 2022). "Similarly, HPGDS was also expressed highly in grades 2, 3, and 4 gliomas lacking the 1p/19q co-deletion, further suggesting that high levels of HPGDS predict poorer patient outcomes." (PMID 36291099, 2022).
ischemic stroke (4 papers, 2019 to 2023). A stroke disorder caused by obstruction of blood flow to the brain, due to thrombotic (local blood clot formation) or embolic (due to a blood clot or other material traveling from another site) event. "tmTNF expressing microglia had an increased expression of HPGDS, which is known to be expressed in activated microglia in the core of the infarct after ischemic stroke and to enhance their differentiation into a phagocytic phenotype." (PMID 31440125, 2019). "Among the upregulated proteins was HPGDS, which is upregulated in microglia and macrophages after ischemic stroke and is likely to promote microglia/macrophage differentiation to the phagocytic phenotype." (PMID 31440125, 2019).
lung adenocarcinoma (3 papers, 2022). A carcinoma that arises from the lung and is characterized by the presence of malignant glandular epithelial cells. "In addition, deletion of the gene encoding HPGDS was found to induce pancreatic carcinogenesis and to increase the severity of lung adenocarcinoma in a mouse model." (PMID 36291099, 2022). "Therefore, the molecular mechanism underlying HPGDS regulating the lipid metabolism pathway in lung adenocarcinoma should be further studied." (PMID 36324576, 2022). "To conclude, we investigated the abnormal lipid metabolism pathway of lung adenocarcinoma by bioinformatics and performed biological experiments to prove that HPGDS can lead to malignant changes by altering the lipid metabolism of lung adenocarcinoma." (PMID 36324576, 2022). "Moreover, in a recent study, HPGDS was considered a prognostic biomarker for lung adenocarcinomas, and it was suggested that HPGDS may provide clues to the aggressiveness of the disease." (PMID 36553500, 2022).
Arthritis (2 papers, 2021 to 2023). Inflammation of a joint. "However, the role of MC-derived PGD2 in the pathogenesis of RA should be determined in MC-deficient experimental arthritis in mice reconstituted with bone marrow-derived MCs obtained from HPGDS-deficient mice." (PMID 33707464, 2021).
cardiomyopathy (2 papers, 2013 to 2024). A disease of the heart muscle or myocardium proper. "Moreover, HPGDS inhibitors can slow the progression of muscle injury and cardiomyopathy." (PMID 38339125, 2024). "In our previous study, we observed an elevated expression of HPGDS and PGD2 in the myocardium during the progression of cardiomyopathy in mdx mice, suggesting the potential involvement of PGD2 in myocardial damage, extending beyond its role in skeletal muscle." (PMID 38339125, 2024). "Our findings confirm the possibility of using HPGDS inhibitor therapy to suppress PGD2 production to treat skeletal muscle disorders and cardiomyopathy." (PMID 38339125, 2024).
food allergy (2 papers, 2017 to 2019). Gastrointestinal disturbances, skin eruptions, or shock due to allergic reactions to allergens in food. "In food antigen-induced mast cell hyperplasia in mice, c-Kit+/FcE-RI+ mast cells in colon sections stained highly positive for hPGDS, and tetranor PGD metabolite, a mast cell-derived PGD2 metabolite, proved to be a specific biomarker for food allergy in patients." (PMID 31226822, 2019).
lupus (2 papers, 2019 to 2021). "Recently, another group addressed the role of basophils in systemic lupus erythematosus development and found that autocrine PGD2 production and CXCR4-dependent stimulation of basophils can be reversed by using a specific hPGDS inhibitor (HPGDS inhibitor I, Cayman)." (PMID 31226822, 2019).
acute respiratory distress syndrome (1 paper, 2021). Progressive and life-threatening pulmonary distress in the absence of an underlying pulmonary condition, usually following major trauma or surgery. "In addition, urinary PGD2 metabolites have been proposed as biomarkers for acute respiratory distress syndrome (ARDS) and lung sections from ARDS patients displayed an extensive immune infiltrate consisting mainly of macrophages and monocytes that stained positive for hPGDS." (PMID 34769126, 2021).
adenoid cystic carcinoma (1 paper, 2022). A malignant tumor arising from the epithelial cells. "For example, HPGDS was differentially expressed in different stages of nine tumors, including those arising from adenoid cystic carcinoma (ACC), BLCA, KICH, and KIRC." (PMID 36291099, 2022).
chronic rhinosinusitis (1 paper, 2017). Chronic form of sinusitis. "For instance, HPGDS expression is enhanced, while microsomal PGE2 synthase is decreased in chronic rhinosinusitis that results in eosinophilic inflammation favoring polyp formation." (PMID 28770200, 2017).